USF2 (upstream transcription factor 2, c-fos interacting)
Diseases named in the same sentence as USF2 in open-access papers (continued):
Sharing a sentence is not in itself a finding about the gene and the disease.
cancer (continued). "Although it is known that USF2 is a phosphoprotein and that CDK5 has an abnormal expression and activity in several human cancers, it is unknown whether USF2 is a substrate for CDK5." (PMID 31013770, 2019). "Thus, understanding the mechanism(s) regulating USF2 function will help to reveal its role in the progression of cancer." (PMID 31013770, 2019). "There are also other studies suggesting a role of USF2 in the development of cancer." (PMID 25741280, 2015). "In addition, USF2 was found to be affected in breast, lung, oral and colorectal cancer suggesting a more general role of USF2 in tumorigenesis." (PMID 25238393, 2014). "Our own previous work on the role of USF2 on the expression of the cancer marker plasminogen activator inhibitor-1 (PAI-1) suggested that USF2 might be phosphorylated by other kinases then PKA." (PMID 25238393, 2014). "However, the exact function of USF2 may depend on the cellular context and in particular this may be important in cancer." (PMID 31013770, 2019). "In summary, we revealed that candidate transcription factors identified from the CRISPR/Cas9 screen including USF2 and USF1, regulate HOXA9 thereby providing a more comprehensive understanding about how the HOXA9 locus is regulated in human cancer cells." (PMID 33001025, 2020). "Thus, due to the correlation of USF2 and CDK5 in partially the same cancers, CDK5 seems to be of special interest in the context of USF2 regulation." (PMID 31013770, 2019). "In addition, in cancer cells, there was a strong tendency of co-occurrence between high LGALS3BP, high USF1, high USF2, and high TGF-β1 expression (p < 0.001) or low LGALS3BP, low USF1, low USF2, and low TGF-β1 expression (p < 0.001)." (PMID 33888686, 2021). "Therefore, it was the aim of the present study to determine whether USF2 can be phosphorylated by CDK5 and to investigate the impact of CDK5-dependent USF2 phosphorylation on cell proliferation and migration in human cancer cells lacking CDK5." (PMID 31013770, 2019).
infection (2 papers, 2020 to 2023). The state of being infected such as from the introduction of a foreign agent such as serum, vaccine, antigenic substance or organism. "Similar to the results with unsorted infected cells, we found that the WT, USF1, and USF2 deficient cells produced a nearly equivalent proportion of productively infected cells at 3 and 4 days post-infection." (PMID 37515158, 2023). "Additionally, infection of the USF knockout Jurkat Tat mHIV-Luciferase cell lines with a Red-Blue-HIV-1 (RBH) reporter virus similarly indicated that USF2 depletion caused the cells to be more resistant to infection." (PMID 37515158, 2023). "We found that the USF2 knockout inhibited reactivation of latent HIV-1 provirus but did not affect the proportion of latently infected cells at four days post-infection." (PMID 37515158, 2023). "Next, the same assay was performed by infecting SEMCas9 cells with three individual lentiviral-mCherry-sgRNAs against USF2 (sgRNA-2,–3 and 5) at ~50% infection efficiency." (PMID 33001025, 2020). "Taken together, these observations indicate that USF2 is important for infection of T cells by HIV-1 through a process that may involve the cellular activation state." (PMID 37515158, 2023). "To further examine the role of USF for regulating latency, we monitored the proportion of productively infected cells for three weeks following infection of wildtype, USF1 KO, and USF2 KO cells." (PMID 37515158, 2023). "Interestingly, although USF2 was required for reactivation of latent provirus, we found that USF2 KO did not affect the proportion of cells that established latency four days following infection." (PMID 37515158, 2023).
psychiatric disorder (1 paper, 2020). A disorder characterized by behavioral and/or psychological abnormalities, often accompanied by physical symptoms. "Twelve known ASD SNPs are associated with validated TF binding sites of YY1, E2F1 and USF2 enriched in neurodevelopmental and neuro-psychiatric disorder PPI network." (PMID 33080834, 2020).
USF2 also shares sentences with these, for which no sentence is quoted: atherosclerosis (3 papers); diabetes (3); acute kidney injury (2); lung adenocarcinoma (2); adenocarcinoma (1); Arthritis (1); biliary atresia (1); cervical cancer (1); chronic kidney disease (1); Cowden syndrome (1); epilepsy (1); follicular thyroid carcinoma (1); glioblastoma (1); Hepatitis B (1); Hepatitis C (1); Infertility (1); iron deficiency (1); Lipid storage disease (1); migraine (1); myeloid leukaemia (1); neurological diseases (1); oral cancer (1); preeclampsia (1); prostate adenocarcinoma (1); pulmonary fibrosis (1); Renal atrophy (1); type 2 diabetes mellitus (1).